CAT (catalase)
Diseases named in the same sentence as CAT in open-access papers (continued):
Sharing a sentence is not in itself a finding about the gene and the disease.
cancer (continued). "In cancer cells, CAT is often found in high concentrations at the plasma membrane and sometimes released in the extracellular matrix." (PMID 32605023, 2020). "In cancer cells, catalase expression is regulated by miR-551b and miR-146a, and inhibition of catalase by these miRNAs promotes ROS accumulation." (PMID 31717786, 2019). "Among the NRF2 targets, catalase overexpression has been shown to protect cancer cells from apoptosis induced by DNA-damaging agents." (PMID 31384396, 2019). "Catalase overexpression has been shown to protect cancer cells from apoptosis induced by DNA-damaging agents, rendering catalase a future therapeutic target." (PMID 31384396, 2019). "Accordingly, targeting the redox status of cancer cells by modulating the catalase expression is emerging as a novel approach to potentiate chemotherapy." (PMID 31212703, 2019). "CAT expression is modified in cancer cell lines that become resistant to chronic exposures to H2O2 or to certain chemotherapeutic agents such as doxorubicin." (PMID 31934266, 2019). "In this context, cancer cells would need very high concentrations of catalase (in the mM order) to protect themselves from the ONOO‒ pathway, which was the only pathway found to generate •OH in a significant amount." (PMID 31810265, 2019). "This study aimed to develop a highly selective controlled catalase-enhanced synergistic photodynamic and photothermal cancer therapy based on gold nanostars." (PMID 31534494, 2019). "Superoxide dismutase (SOD) and Catalase (CAT) are major enzymatic antioxidants involved neutralize ROS in cancer cells." (PMID 31013662, 2019). "The particles were then modified with catalase and the targeting moiety c(RGDyK), which can specifically recognize cancer cells 25,26." (PMID 31534494, 2019). "Although NADPH-independent catalase activity has been reported to decrease with cancer progression, the remarkable antioxidant capacity is one of the reasons for chemoresistance in advanced cancer cells." (PMID 31929855, 2019). "Although mechanisms controlling CAT expression have been partially elucidated, the decreased CAT expression in cancer cells still remains an unanswered question." (PMID 31934266, 2019). "For a transformed cell to reach the state of a cancer cell, it needs to protect itself from the apoptosis-inducing signalling pathways, which is achieved by relocating intracellular catalase into the outer cell membrane." (PMID 31810265, 2019). "Cancer cells that are resistant to ROS-induced apoptosis can overcome the cytotoxic activity of exogenous H2O2 by presenting catalase in the outer layer of the cell membrane." (PMID 31687089, 2019). "The lower levels of antioxidant enzymes such as catalase, glutathione peroxidase, reductase and their respective cofactors in cancer cells compared to normal cells amplify this phenomenon." (PMID 31741707, 2019). "The toxicity of AscH− to cancer cells can be inhibited by either catalase, which removes H2O2, or iron chelators that inhibit redox cycling." (PMID 29351198, 2018). "Oxygen radical absorbance capacity values are associated with the increases in CAT and SOD activities and the reduction in reactive oxygen species, in which the extract has a significant therapeutic and preventive potentials of cancer and diabetes." (PMID 29849880, 2018). "Additional regulatory levels clarifying this altered catalase expression in cancer cells were also explored." (PMID 29535798, 2018). "Cancer cells possess much higher innate hydrogen peroxide (H2O2) but much lower catalase levels than normal cells." (PMID 30410055, 2018). "The cancer cell clonogenic killing capacity of GC/AscH− was completely inhibited by catalase overexpression, demonstrating that H2O2 was causally related to the cancer cell clonogenic killing." (PMID 29351198, 2018).
cancer (continued). "DEN-2AAF-induced CAT activity has been similarly shown to be increased in cancer cells, most likely, to favor cell proliferation by inducing genetic instability and activation of oncogenes." (PMID 29352129, 2018). "In order to eliminate ROS, cancer cells also stimulate the antioxidant system, such as MnSOD, catalase, and glutathione peroxidase." (PMID 30595797, 2018). "We explored a potential role of catalase during the acquisition of cancer cell resistance to chemotherapeutic agents." (PMID 29535798, 2018). "We observed an upregulation of the organic cation transporter SLC22A16 following exposure with cold plasma-derived oxidants in a subset of cancer cell lines, which was inhibited by antioxidant catalase and Ca2+ channel inhibitor BTP2." (PMID 30518936, 2018). "In agreement with previous results regarding catalase gene transcription as the main regulator of catalase expression in cancer cells, we observed that ATO decreased the transcriptional activity of catalase gene promoter." (PMID 29467594, 2018). "Take the catalase as an example, its expression in cancer cells are less than the corresponding normal cells in many studies." (PMID 27845910, 2017). "Our evidence that catalase activity was reduced in cancer cell lines after apigenin exposure is compatible with the mechanism of action of apoptosis induction." (PMID 28191273, 2017). "This is consistent with that the overexpression of CAT leads to a less aggressive phenotype of cancer cells." (PMID 28426704, 2017). "The amount of CAT activity in the cancer group (Group 2) was also significantly (p < 0.05) reduced in comparison with the normal group (Group 1)." (PMID 28872373, 2017). "Treatment with CAT-SKL—a re-engineered protein form of the antioxidant enzyme catalase—inhibited cancer stem-like cells (CSCs), and treatment with the EGFR-specific SMKI erlotinib inhibited non-CSCs." (PMID 28281569, 2017). "In HBC cells, the inhibition of catalase bioactivity is coupled to an increase of intracellular H2O2 levels necessary for the proliferation of cancer cells." (PMID 27848965, 2016). "Here, the authors report that homocysteine inactivates catalase by modifying the heme group, impairing cellular redox homeostasis, and show that this modification occurs in cancer cells and in a cellular model of Parkinson's disease." (PMID 27848965, 2016). "We determine that not only do endogenous antioxidants such as catalase contribute to ROS-induced cell death, but also cell membrane properties play a critical role in the efficacy of ROS as a cytotoxic mechanism against cancer cells vs. normal cells." (PMID 27278439, 2016). "In contrast, the amount of CisPt taken up by cancer cells is highly toxic because these enzymes, particularly catalase, are poorly expressed in cancer cells." (PMID 26725847, 2016). "The results of RT-PCR showed that the mRNA expression level of HO-1, SOD, GPx, and CAT in HCC tissue significantly upregulated in comparison with those in adjacent cancer tissue and normal tissue (all P <0.05)." (PMID 27227932, 2016). "Significantly, candidate genes MMP1, CDC45, and CAT were also, respectively, enriched in the pathway in cancer, cell cycle, and methane metabolism." (PMID 27034707, 2016). "The results of this study demonstrated that the levels of SOD and CAT in the homogenised colon treated with the CdCl2(C14H21N3O2) complex significantly (p < 0.05) increased when compared with the cancer control group." (PMID 26201720, 2015). "We repeated our experiments with addition of catalase (50 U/mL) to the cancer cells during 72 h of incubation with BTE extract and we did not detect any changes of hydrogen peroxide levels with or without addition of catalase." (PMID 25825685, 2015). "An increased ROS production has been observed in other cancers, and in some cases the cancer cells express catalase (the enzyme that metabolizes H2O2) in excess and in addition produce large amounts of H2O2." (PMID 26538833, 2015).
cancer (continued). "We found that the treated groups had significantly higher enzymatic antioxidant defence activity of SOD and CAT when compared with the cancer control group." (PMID 26201720, 2015). "In pH-dependent pro-oxidant effect conditioned by inhibition of catalase activity in cancer cells, CNPs are only capable of catalyzing the conversion of highly unstable superoxide to far more stable H2O2." (PMID 26097523, 2015). "The efficacy of EGCG to bind with catalase and render its activity in cancer cells definitely represents a fascinating tool in the field of oncology." (PMID 25025898, 2014). "Although some cancer cell lines express low catalase activity, this cannot fully explain the selective sensitivity of cancer cells to hydrogen peroxide." (PMID 25279352, 2014). "Some researchers are now using adenovirus containing SOD and CAT in the treatment of various cancers both in vitro and in vivo." (PMID 24511533, 2014). "In contrast, the amount of cisplatin taken up by cancer cells will be very toxic for them given the modest quantity of protective enzymes, particularly catalase, they express." (PMID 24511533, 2014). "The antioxidative enzyme catalase is important to protect cancer cells against cytotoxic hydrogen peroxide." (PMID 22551313, 2012). "On the basis of our data, we were able to show a correlation between catalase activity and resistance of cancer cell lines to the ascorbic acid induced cytotoxic effect." (PMID 22551313, 2012). "Compared to other cancer cell lines, the level of catalase protein was significantly higher in BT-20 cells highly resistant to the ascorbic acid mediated cytotoxic effect compared to the other cancer cell lines." (PMID 22551313, 2012). "The results indicate that catalase is important for the resistance of cancer cells to oxidative stress mediated by hydrogen peroxide." (PMID 22551313, 2012). "It seems that many cancers demonstrate substantially lower catalase activity than normal tissues, allowing cancers to generate a moderate intracellular level of oxidative stress to aid their proliferation and survival." (PMID 22551313, 2012). "The purpose of this study was to analyse the impact of catalase, an important hydrogen peroxide-detoxifying enzyme, on the resistance of cancer cells to ascorbic acid mediated oxidative stress." (PMID 22551313, 2012). "ROS levels have been found to be significantly higher in cancer cells than in normal cells, and the activity of antioxidant enzymes such as glutathione peroxidase, catalase and SOD has been shown to be significantly lower in cancer patients than in controls." (PMID 21418589, 2011). "For this reason, catalase inhibitors can contribute to the resensitization of cancer cells to ROS-induced apoptosis." (PMID 24281116, 2010). "Together with SOD, catalase also has a central role in the protection of cancer cells against intrinsic oxidative stress." (PMID 24281116, 2010). "ELISA detected increased PADI4 and cAT levels in the blood of patients with various malignant tumors compared to those in patients with chronic inflammation and benign tumors." (PMID 19183436, 2009). "Spontaneous monocyte-mediated cytotoxicity towards cancer cells was inhibited by superoxide dismutase, catalase, deferoxamine and hydrazide, implicating the role of superoxide anion, hydrogen peroxide, hydroxyl radical and hypohalite." (PMID 10070862, 1999). "Multiple mitochondrial proteins in cancer cells can likely undergo CAT-tailing in a similar way." (PMID 38798583, 2026). "Taken together, these results suggest that the anticancer activity of LPE involves the complex modulation of cellular redox homeostasis through the inhibition of catalase and other key oxidative enzymes, creating conditions incompatible with cancer cell survival." (PMID 41596250, 2026).
cancer (continued). "In addition, visfatin increases the activity of antioxidant enzymes [superoxide dismutase (SOD), catalase (CAT), and glutathione peroxidase], which induces protection of cancer cells from cytotoxic damage by reactive oxygen species." (PMID 40170859, 2025). "Research shows that cancer cells are characterized by reduced activity of many antioxidant enzymes, such as superoxide dismutase and catalase, which may damage DNA structure and cancer." (PMID 40864765, 2025). "Nanoceria (<5 nm) possess the catalytic ability to mimic natural enzymes such as superoxide dismutase, peroxidase, and catalase, enabling effective scavenging of reactive oxygen species (ROS), which play a central role in the pathogenesis of chronic inflammation and cancer." (PMID 41550883, 2025). "Accordingly, recent studies have moved towards antioxidants such as Lactate dehydrogenase (LDH), superoxide dismutase (SOD) and catalase (CAT), and towards stimulants of ROS production in cancer cells, such as iron, as its excess leads to the production of ROS via the Fenton reaction." (PMID 40450119, 2025). "These compounds may sensitize cancer cells to ROS-mediated damage by downregulating antioxidant defenses (e.g., glutathione, catalase), thereby amplifying AgNPs’ intrinsic oxidative effects." (PMID 40808211, 2025). "Similarly, catalase (CAT) decomposes hydrogen peroxide in cancer cells, preventing the formation of toxic free radicals and thereby inhibiting apoptosis." (PMID 39945813, 2025). "Third, the study did not include all antioxidant systems, such as other key enzymes, for instance, catalase, which may also play significant roles in cancer progression and redox regulation." (PMID 41262897, 2025). "Similarly, CAT-mimetic platinum nanoparticles have been shown to improve chemotherapeutic outcomes by relieving cancer hypoxia, thereby enhancing drug efficacy." (PMID 40722961, 2025). "These latter findings suggest that low levels of PPARγ, peroxisomes, and catalase in cancer cells may contribute to tumour progression, and increasing those levels can potentially inhibit cancer growth." (PMID 41373547, 2025). "In our study, the decreased SOD and catalase activities in the relapsed pediatric patient groups may have been due to the increased oxidative stress produced from cancer recurrence, which consumed these enzymes." (PMID 39334568, 2024). "Previous studies have shown that the increased sensitivity of PDAC cells to P-AscH− may be due to a H2O2 mechanism, suggesting the difference lies in cancer cells having less catalase activity and a lower capacity to remove H2O2." (PMID 38539894, 2024). "Cancer cells often have lower levels of catalase compared to normal cells." (PMID 38539894, 2024). "In addition, catalase, an enzyme that converts hydrogen peroxide, is usually downregulated in cancer cells." (PMID 38483584, 2024). "Previous studies have also shown that this pro-oxidant effect in cancer cells is accompanied by a reduced activity of important antioxidant enzymes, such as catalase (CAT) and glutathione reductase (GR), while the activity of superoxide dismutase (SOD) remains unchanged." (PMID 39766242, 2024). "Catalase down-regulation in cancer cells reduced antioxidant capacity leading to ROS accumulation." (PMID 38600497, 2024). "However, the role of Catalase in cancer is still controversial, and its expression varies in multiple cancers." (PMID 38424181, 2024). "The expression of catalase and other antioxidant enzymes is often altered in cancer, resulting in aberrant levels of ROS, and catalase as well as other antioxidant enzymes play an important dichotomous role in cancer." (PMID 39540258, 2024). "ROS can trigger autophagy via several mechanisms involving autophagy-related protease 4 (Atg4), catalase, and the mitochondrial electron transport chain, leading to both cell survival and death, which may be selective for cancer cells." (PMID 39334754, 2024).
cancer (continued). "CAT inhibitors are known to increase ROS production in cancer cells and to induce ferroptosis." (PMID 38406279, 2024). "Recently, some data have indicated that irinotecan may worsen hepatic oxidative stress by inducing the formation of ROS and lipid peroxides while simultaneously lowering GSH, superoxide dismutase (SOD), and catalase (CAT) in cancer cells." (PMID 38398072, 2024). "An oxygen-generating implantable material consisting of alginate beads encapsulating CaO2 and catalase has been developed by Huang and colleagues as an active carrier for doxorubicin, with the aim to increase the drug sensitivity in cancer cells undergoing hypoxia-induced chemo-resistance." (PMID 38791232, 2024). "Moreover, IGHG2, HPT, and A2MG identified in stool-related cancer samples, along with catalase detected in advanced pre-cancerous lesions, have been previously reported elevated in both cancerous and advanced non-cancerous lesions." (PMID 38612533, 2024). "Altered levels of catalase have been reported in various cancer tissues compared to healthy cells." (PMID 38483584, 2024). "Increased catalase expression and activity in tumors may promote cancer cell survival and progression." (PMID 39170262, 2024). "In cancer cells, there is a decrease in antioxidant levels, increase in free radicals, and a disruption of mitochondrial membrane potential, whereas normal cells show elevated catalase levels and insensitivity to hydrogen peroxide." (PMID 39204317, 2024). "In relation to the significance of CAT activity in cancer, it has been shown that CAT activity inhibition significantly raises the level of oxidative stress and hydrogen peroxide, which kill cancer cells." (PMID 38529192, 2024). "The obtained results thus indicate that regulation of catalase expression in cancer cells may represent a new prooxidant approach to enhance the effectiveness of chemotherapy." (PMID 38483584, 2024). "However, the overexpressed CAT gene in response the greater doses up to 80 μg/mL can be due to MuSCF-NPs’ potential to scavenge free radicals and give time to the cancer cell to activate its compensatory mechanisms and drug resistance strategies." (PMID 38600497, 2024). "Similarly, CAT, another key enzyme involved in the detoxification of ROS, also showed altered expression in cancer." (PMID 39767718, 2024). "Catalase expression is altered in cancer cells, a fact that plays an important dichotomous role." (PMID 38891864, 2024). "Notably, the reversal of these effects by extracellular catalase emphasizes the roles of extracellular H2O2 in mediating P-AscH−‘s anti-cancer actions." (PMID 37760080, 2023). "Similarly, co-treatment of GLPs and doxorubicin of cancer cells reduced cardiotoxicity, lipid peroxidation, and creatinine kinase while significantly improving antioxidant enzymes CAT, GSH, and GPx activity." (PMID 38104078, 2023). "Occasional exceptions can be found; for example, all 13 tRNA-Glu-TTC genes are active in one particular metastasis (M_013), but this anomaly does not reflect the general hyperacetylation of tRNA loci in this sample, as only three out of nine tRNA-iMet-CAT genes are active in the same cancer." (PMID 37509247, 2023). "CAT and SOD are also enzymes that cells use to fight peroxidation states, and studies have shown that glutathione depletion can make cancer cells more sensitive to oxidative stress and thereby more susceptible to some pro-apoptotic genes or anti-cancer drugs." (PMID 37274227, 2023). "Moreover, this cancer cell killing was shown to depend on H2O2 release because addition of catalase which breaks down the peroxide to water and oxygen, inhibited the neutrophil mediated killing of the cancer cells." (PMID 36066649, 2023).